NTF4 (neurotrophin 4)
Description:
Target-derived survival factor for peripheral sensory sympathetic neurons. May promote ameloblast differentiation and subsequent reduction in proliferation of ameloblasts (By similarity).
Synonyms: NT-4; NT-5; NTF5; NT-4/5; GLC1O; GLC10; NT4; NT5
Tractability: Small molecule: it has a binding pocket of medium quality. Antibody: UniProt places it where antibodies can reach, with high confidence; its Gene Ontology location is reachable by antibodies, with high confidence; UniProt predicts a signal peptide or a membrane-spanning region.
Gene: Protein-coding gene on chromosome 19 (49,061,066 to 49,065,076, reverse strand). Ensembl gene ENSG00000225950.
Subcellular location: Secreted
Subcellular location (Human Protein Atlas): Golgi apparatus; Predicted to be secreted
Pathways (Reactome):
Signal Transduction: Activated NTRK2 signals through FRS2 and FRS3; Activated NTRK2 signals through PI3K; Activated NTRK2 signals through PLCG1; Activated NTRK2 signals through RAS; NTF4 activates NTRK2 (TRKB) signaling; PI5P, PP2A and IER3 Regulate PI3K/AKT Signaling; PIP3 activates AKT signaling
Disease: Constitutive Signaling by Aberrant PI3K in Cancer
Gene Ontology:
Molecular function: protein binding; growth factor activity; nerve growth factor receptor binding; signaling receptor binding
Biological process: adult locomotory behavior; ameloblast differentiation; cell surface receptor protein tyrosine kinase signaling pathway; epidermis development; ganglion mother cell fate determination; long-term memory; modulation of chemical synaptic transmission; negative regulation of neuron apoptotic process; nerve development; nerve growth factor signaling pathway; neuron projection morphogenesis; sensory organ boundary specification
Cellular component: extracellular region; synaptic vesicle
Genetic constraint (gnomAD): Loss-of-function variants: 4 observed, 5.98 expected, observed/expected ratio (o/e) 0.67, 90% interval 0.33 to 1.49. That is too few expected variants to judge how well the gene tolerates losing a copy. Missense variants: 260 observed, 285.52 expected, observed/expected ratio (o/e) 0.91, 90% interval 0.82 to 1.01. Synonymous variants: 127 observed, 119.49 expected, observed/expected ratio (o/e) 1.06, 90% interval 0.92 to 1.23.
Gene-disease validity (ClinGen):
ClinGen rates the evidence that NTF4 causes each of these diseases.
glaucoma 1, open angle, O (autosomal dominant): Disputed.
Homologues: Orthologues: chimpanzee NTF4 (100% identical), macaque NTF4 (99% identical), dog NTF4 (93% identical), pig NTF4 (91% identical), mouse Ntf5 (91% identical), rat Ntf4 (90% identical), guinea pig NTF4 (90% identical), rabbit NTF4 (89% identical), tropical clawed frog ntf4 (50% identical). Paralogues in human: BDNF (43% identical), NTF3 (42% identical), NGF (35% identical).
Diseases named in the same sentence as NTF4 in open-access papers:
NTF4 is named in the same sentence as 106 diseases in open-access papers, as found by Europe PMC text mining. Sharing a sentence is not in itself a finding about the gene and the disease. The quoted sentences say what the papers report.
glaucoma (13 papers, 2010 to 2025). Increased pressure in the eyeball due to obstruction of the outflow of aqueous humor. "A recent study identified mutations within the neurotrophin-4 (NTF4) gene to account for 1.7% of primary open-angle glaucoma (POAG) in Europeans." (PMID 20806036, 2010). "The neurotrophin-4 (NTF4) gene has been recently implicated in primary open-angle glaucoma (POAG)." (PMID 22815630, 2012). "Therefore it is likely that pathogenic mutations in these genes, including NTF4, would cause glaucoma together with other factors, such as the general genetic backgrounds, gene risk variants and environmental risk." (PMID 22815630, 2012). "Additional local risk factors might have acted, additively or interactively, with mutant NTF4 in this patient to cause glaucoma." (PMID 22815630, 2012). "The recent identification in glaucoma patients, of seven different heterozygous NTF4 mutations reveals a crucial role of the neurotrophin signaling system in preventing neural degeneration, thus supporting the possibility of another pathway in the pathogenesis of glaucoma." (PMID 20806036, 2010). "Brain-derived neurotrophic factor, neurotrophin-3, and neurotrophin-4 are less studied neurotrophins in the ocular surface, even though brain-derived neurotrophic factor is well characterized in glaucoma, retina, and neuroscience." (PMID 36430547, 2022). "In contrast to NGF, investigations into effects of brain-derived neurotrophic factor, neurotrophin-4 (bind TrkB), and neurotrophin-3 (bind to TrkC) on the ocular surface are sparse, certainly less than those on the retina and on glaucoma." (PMID 36430547, 2022). "As an optic nerve disease signature, NTF4 has been commonly used for the assessment and identification of glaucoma." (PMID 33511023, 2021). "Other genetic factors, e.g., optic atrophy 1 (OPA1), apolipoprotein E, E-cadherin, neurotrophin-4 (NTF-4) and opticin (OPTC), have been reported to elevate the risk of retinal degeneration, a characteristic of glaucoma." (PMID 22509108, 2012). "myocilin (MYOC), optineurin (OPTN), WDR36 and neurotrophin-4 (NTF4) in primary open angle glaucoma (POAG) and CYP1B1 and LTBP2 in congenital and developmental glaucomas." (PMID 21150032, 2011). "Based on their findings of the association between mutations in NTF4 and POAG, Pasutto and coworkers have demonstrated an impaired TrkB activation as a possible pathway in the pathophysiology of glaucoma." (PMID 20806036, 2010). "In addition, the role of neurotransmitters such as glutamate, glycine, dopamine, serotonin, etc., and neurotrophins, such as the brain-derived neurotrophic factor (BDNF), neurotrophin-3 (NT3), and neurotrophin-4/5 (NT4/5) in glaucoma, has also been extensively investigated." (PMID 37305138, 2023). "Therefore, it is likely that a NTF4 mutation alone is not sufficient to explain glaucoma pathogenesis, and other factors should have played a role." (PMID 22815630, 2012). "NTF4 is not found to be candidate gene for glaucoma in several studies." (PMID 29540704, 2018). "WD repeat domain 36 (WDR36), neurotrophin 4 (NTF4), ankyrin repeat and SOCS box-containing 10 (ASB10), and TANK-binding kinase 1 (TBK1) are other genes that have also been reported to be glaucoma-causing genes, but are controversial or have not yet been widely replicated." (PMID 22509100, 2012). "However, given the recent contradictory findings for NTF4, the screening of NTF4 in POAG patients of other ethnicities and meta-analyses of different studies in POAG patients are required to establish the extent of involvement of NTF4 in glaucoma." (PMID 20806036, 2010).
cognitive deficits (7 papers, 2014 to 2025). "This suggests that TrkB, a receptor for multiple neurotrophins (BDNF and neurotrophin 4), may be a more sensitive and worthy indicator of cognitive impairment than serum BDNF." (PMID 36683819, 2022).
breast carcinoma (5 papers, 2012 to 2024). "What's more, clinical data revealed NTF4 may be a new potential biomarker for predictive early breast cancer risk for metastasis." (PMID 36632451, 2023). "GSEA analysis revealed that a number of NTF4 target proteins are enriched in breast cancer PI3-kinase (PI3K) signaling pathways." (PMID 36632451, 2023). "In summary, NTF4 was shown to play both pro-metastatic and anti-tumorigenic roles in breast cancer progression." (PMID 36632451, 2023). "Secondly, NTF4 is a new regulator of breast cancer EMT and cancer progression, which targets PRKDC (DNA-PKcs) and ANXA1 and activate AKT and NF-κB pathways." (PMID 36632451, 2023). "We also determined the expression levels of NTF4 in two normal human mammary epithelial cell lines and eight well-characterized breast cancer cell lines." (PMID 36632451, 2023). "The area under the ROC curve suggested that NTF4 had accuracy for prediction of breast cancer (AUC=0.839, CI: 0.785-0.839)." (PMID 36632451, 2023). "In this study, we present several unexpected findings that demonstrate important but complex roles for NTF4 in malignant progression and metastasis of breast cancer." (PMID 36632451, 2023). "Significantly decreased expression of NTF4 was observed in primary breast cancer tissue, with increased expression in metastatic lymph nodes, which was consistent with results of the RNA-Seq screening." (PMID 36632451, 2023). "The expression of NTF4 was significantly higher in metastatic breast cancer cells, suggesting that NTF4 promotes breast cancer cell metastasis in vivo." (PMID 36632451, 2023). "Herein, we report that neurotrophin 4 (NTF4) plays a dual role in breast cancer proliferation and metastasis." (PMID 36632451, 2023). "Breast cancer patients with high levels of NTF4, especially in the early stage, have a poorer clinical prognosis." (PMID 36632451, 2023). "Phosphorylation of GSK-3β (Ser9) was promoted by activated PRKDC/AKT signaling, while the expression of SNAIL was increased and E-cadherin was decreased in NTF4 over-expressing breast cancer cells." (PMID 36632451, 2023). "Our findings identified an unexpected dual role for NTF4 in breast cancer which contributes to early metastasis of the disease." (PMID 36632451, 2023). "Flow cytometry analysis also showed that NTF4 significantly increased the number of apoptotic breast cancer cells." (PMID 36632451, 2023). "As well, NTF4 suppresses the proliferation of breast cancer cells by increasing the phosphoserine and sumoylation level of ANXA1 and the interaction of ANXA1 with importin β." (PMID 36632451, 2023). "Taken together, these results suggest that NTF4 suppresses breast cancer cell proliferation in vitro and tumor growth in vivo." (PMID 36632451, 2023). "CCK-8 cell proliferation assays demonstrated over-expression of NTF4 to inhibit breast cancer cell proliferation." (PMID 36632451, 2023). "The expression levels of NTF4 in 14 matched pairs of human breast cancer and normal breast tissue were assessed by quantitative real-time polymerase chain reaction (qRT-PCR)." (PMID 36632451, 2023). "Taken together, these results demonstrate NTF4 to promote breast cancer cell migratory and invasive behaviors in vitro and lung metastatic potential in vivo." (PMID 36632451, 2023). "Treatment of breast cancer cells with MG132 demonstrated that NTF4 reduced the generation of E-cadherin, which is consistent with qPCR results." (PMID 36632451, 2023). "Colony growth assays demonstrated expression of NTF4 to decreased colony formation of breast cancer cells." (PMID 36632451, 2023). "We next examined whether NTF4 affects migratory and invasive properties of breast cancer cells in vitro." (PMID 36632451, 2023). "Herein, we report that NTF4 plays a dual role in the malignant progression of breast cancer." (PMID 36632451, 2023). "In this study, we found NTF4 to promote breast cancer EMT, invasion, and migration." (PMID 36632451, 2023).
breast carcinoma (continued). "Firstly, NTF4 plays both anti-tumorigenic and pro-metastatic roles in breast cancer progression." (PMID 36632451, 2023). "After CHX treatment of breast cancer cells, NTF4 was found to increase the stability of SNAIL." (PMID 36632451, 2023). "Thus, we focused on PRKDC and ANXA1 and found both proteins to be significantly increased in NTF4 stably expressing breast cancer cells, as well as constituents of an activated AKT signaling pathway." (PMID 36632451, 2023). "Moreover, inhibition of PRKDC/AKT signaling and ANXA1 effectively rescues NTF4-mediated breast cancer metastasis and invasion." (PMID 36632451, 2023). "NTF4 contributes to breast cancer cell survival by mediating cell resistance to apoptosis." (PMID 36632451, 2023). "These new findings provide mechanistic insight into the functional role of NTF4 in the regulation of breast cancer development and progression and may have specific clinical relevance." (PMID 36632451, 2023). "Clinical data showed high levels of NTF4, especially in the early stage, to be associated with poor clinical outcomes, supporting the notion that metastasis, rather than primary cancer, was the major determinant of breast cancer mortality for patients." (PMID 36632451, 2023). "Hence, NTF4 or NTF4 combined with ANXA1 may be biomarkers for breast cancer prognosis, especially for early stage breast cancer patients at risk for metastasis." (PMID 36632451, 2023). "Thus, we speculated that overexpression of NTF4 would induce breast cancer cell apoptosis by ANXA1 nuclear translocation." (PMID 36632451, 2023). "Therefore, NTF4 may serve as a prognostic marker and a potential therapeutic target for breast cancer." (PMID 36632451, 2023). "NTF4 promoted epithelial-mesenchymal transition (EMT), cell motility, and invasiveness of breast cancer cells in vitro and in vivo." (PMID 36632451, 2023). "Furthermore, subgroup survival analysis at stage I showed the group with high NTF4 expression to have poorer PFS (p<0.05), suggesting that the upregulation of NTF4 in early breast cancer patients may serve as a predictive biomarker for progression or metastasis." (PMID 36632451, 2023). "As shown in, normal mammary epithelial cell lines (MCF10A and HMEC), luminal-type breast cancer cell lines (T47D, ZR-75-1), and the metastatic cell line (MDA-MB-468) expressed relatively high levels of NTF4 compared to the other cell lines." (PMID 36632451, 2023). "As well as, clinical data showed high levels of NTF4, especially in the early stage, to be associated with poor clinical outcomes, supporting the notion that metastasis, rather than primary cancer, was the major determinant of breast cancer mortality for patients." (PMID 36632451, 2023). "By using IF assays, we found that NTF4 upregulated the expression of PRKDC, and that NTF4 and PRKDC co-localized in breast cancer cells." (PMID 36632451, 2023). "We hypothesized that NTF4 combined with ANXA1 may be combined predictive and therapeutic targets for breast cancer." (PMID 36632451, 2023). "However, no studies have systematically investigated a role for NTF4 in the tumorigenesis and metastatic progression of breast cancer." (PMID 36632451, 2023).
ischemic stroke (5 papers, 2018 to 2026). A stroke disorder caused by obstruction of blood flow to the brain, due to thrombotic (local blood clot formation) or embolic (due to a blood clot or other material traveling from another site) event. "EA combined with mesenchymal stem cell transplantation may improve the recovery of neurological function and upregulate the expression of neurotrophic factors, for instance neurotrophin-4/5 (NT4) and BDNF, involved in neurogenesis in mice with ischemic stroke." (PMID 30618558, 2018). "MSCs and EA treatment could improve the expression levels of trophic factors such as brain-derived neurotrophic factor (BDNF), neurotrophin-4 (NT4), and vascular endothelial growth factor (VEGF) in ischemic stroke, which are all very helpful for brain tissue regeneration." (PMID 35211177, 2022).
colorectal cancer (4 papers, 2021 to 2025). A primary or metastatic malignant neoplasm that affects the colon or rectum. "NTF4, significantly overexpressed in colorectal cancer, was associated with poor overall survival and advanced TNM stage." (PMID 34535962, 2021). "Additionally, NTF4, known as a neurotrophic factor, has been implicated in promoting the growth and metastasis of colorectal cancer and gastric cancer cells." (PMID 39539669, 2024). "For example, NTF4 is upregulated in colorectal cancer and mediates CRC development through regulation of EMT and autophagy." (PMID 36118855, 2022). "NTF4 promoted tumorigenesis and development of colorectal cancer through autophagy regulation." (PMID 34535962, 2021).
depression (4 papers, 2019 to 2024). "However, the therapeutic effects of VD3 on the chronic unpredictable mild stress (CUMS) model of depression, and whether the antidepressant-like action of VD3 involves BDNF, neurotrophin-3 (NT-3), neurotrophin-4 (NT-4), and the HPA axis in long-term OVX adult rats remain unknown." (PMID 31357443, 2019).
epilepsy (4 papers, 2017 to 2025). A brain disorder characterized by episodes of abnormally increased neuronal discharge resulting in transient episodes of sensory or motor neurological dysfunction, or psychic dysfunction. "TrkB, on the other hand, is activated by brain-derived neurotrophic factor (BDNF)- and neurotrophin-4 (NT-4)-binding and has been demonstrated in epilepsy studies to function in neural kindling." (PMID 41155675, 2025). "Ganoderma lucidum spore inhibits the expression of NF-κB in the brain of rats with epilepsy and the expression of N-Cadherin in hippocampal neurons, while enhancing neurotrophin-4 expression in hippocampal neurons." (PMID 28423368, 2017).
retinal degeneration (4 papers, 2012 to 2021). Degeneration of the retina. "The authors then used this system to deliver neurotrophin-4 (NT-4), which is known to protect neurons in models of retinal degeneration." (PMID 33505247, 2020).
Anxiety (3 papers, 2014 to 2020). Intense feelings of nervousness, tension, or panic often arise in response to interpersonal stresses. "In this study besides BDNF, we did not investigated the other members of the neurotrophin family which also includes Nerve Growth Factor (NGF), Neurotrophin-3 (NT-3) and Neurotrophin-4/5 (NT-4/5) because the available data indicate that they are not useful as biomarkers of anxiety." (PMID 26539329, 2015).
Pruritus (3 papers, 2021 to 2023). Pruritus is an itch or a sensation that makes a person want to scratch. "Sorouret al. measured the levels of neurotropins, a group of neurological mediators causing pruritus in skin (brain-derived nerve growth factor (BDNF), neurotrophin-4 (NT-4)) in CKD-aP patients." (PMID 34437400, 2021).
Cerebral atrophy (2 papers, 2021 to 2024). Atrophy (wasting, decrease in size of cells or tissue) affecting the cerebrum. "When neuroprotective factors, such as nerve growth factor, brain-derived neurotrophic factor (BDNF), neurotrophin 3 (NT-3), and neurotrophin 4/5 (NT-4/5) are deficient in MS patients, the influx of PBMC cells to the CNS can make up for this, slowing the rate of cerebral atrophy." (PMID 39201606, 2024).
gastric cancer (2 papers, 2022 to 2024). A primary or metastatic malignant neoplasm involving the stomach. "NTF4 was also reported to be upregulated in gastric cancer tissues and predicted poor overall survival and progression-free survival in GC patients." (PMID 36034210, 2022).
peripheral nerve injury (2 papers, 2018 to 2019). Injury to a peripheral nerve. "Previous studies on Slit focusing on SCs suggested that peripheral nerve injury could lead to the expression of various neurotrophic factors in SCs, including NGF, BDNF, neurotrophin 4/5, insulin growth factor 1 and 2, and Slit2 and Slit3." (PMID 31607866, 2019).
allergies (1 paper, 2020). "Increased expression of neurotrophin-3 and neurotrophin-4 was previously reported in allergies by several papers, although they were not studied as extensively as NGF or BDNF." (PMID 32596360, 2020).
autism (1 paper, 2017). Persistent deficits in social interaction and communication and interaction as well as a markedly restricted repertoire of activity and interest as well as repetitive patterns of behavior. "Children with autism show low expression levels of Neurotrophin-4 (NTF4) in blood, which have been correlated to impairments in neuroplasticity." (PMID 28751869, 2017).
breast tumors (1 paper, 2023). "In this study, we reported that NTF4 was downregulated in primary breast tumors but upregulated in normal breast tissues and in metastatic tissues." (PMID 36632451, 2023).